ZNF460 (zinc finger protein 460)
Description:
May be involved in transcriptional regulation.
Synonyms: ZNF272; HZF8
Tractability: PROTAC: UniProt records ubiquitination sites on it; ubiquitination databases record sites on it; its protein half-life has been measured.
Gene: Protein-coding gene on chromosome 19 (57,279,982 to 57,296,357, forward strand). Ensembl gene ENSG00000197714.
Subcellular location: Nucleus
Subcellular location (Human Protein Atlas): Nucleoplasm
Pathways (Reactome):
Gene expression (Transcription): Generic Transcription Pathway
Gene Ontology:
Molecular function: protein binding; sequence-specific double-stranded DNA binding; DNA-binding transcription factor activity, RNA polymerase II-specific; RNA polymerase II cis-regulatory region sequence-specific DNA binding
Biological process: regulation of DNA-templated transcription; regulation of transcription by RNA polymerase II
Cellular component: nucleus
Genetic constraint (gnomAD): Loss-of-function variants: 1 observed, 8.66 expected, observed/expected ratio (o/e) 0.12, 90% interval 0.04 to 0.55. That is too few expected variants to judge how well the gene tolerates losing a copy. Missense variants: 477 observed, 754.75 expected, observed/expected ratio (o/e) 0.63, 90% interval 0.58 to 0.68. Synonymous variants: 262 observed, 276.07 expected, observed/expected ratio (o/e) 0.95, 90% interval 0.86 to 1.05.
Homologues: Orthologues: chimpanzee ZNF460 (99% identical), macaque ZNF460 (98% identical), dog ZNF460 (58% identical). Paralogues in human: ZNF724 (43% identical), ZNF543 (43% identical), ZNF7 (43% identical), ZNF708 (43% identical), ZNF33B (43% identical), ZNF728 (42% identical), ZNF879 (42% identical), ZNF595 (42% identical), ZNF85 (42% identical), ZNF41 (42% identical), ZNF568 (42% identical), ZNF585B (41% identical), and 164 more.
Diseases named in the same sentence as ZNF460 in open-access papers:
ZNF460 is named in the same sentence as 18 diseases in open-access papers, as found by Europe PMC text mining. Sharing a sentence is not in itself a finding about the gene and the disease. The quoted sentences say what the papers report.
colon cancer (5 papers, 2021 to 2025). "In previous studies, excessive expression of ZNF460 was implicated in adverse outcomes of colon cancer and enhanced invasive capacity." (PMID 37057209, 2023). "In conclusion, these results suggested that overexpression of ZNF460 was not only associated with lymph node metastasis of colon cancer, but also with geographical region and race." (PMID 33976729, 2021). "High expression of ZNF460 represented poor prognosis and might be associated with metastasis of colon cancer." (PMID 33976729, 2021). "Hao and co-workers have shown that hyperexpression of ZNF460 is related to adverse prognosis and that it facilitates cell migration in colon cancer via the JAK2/STAT3 signaling pathway." (PMID 37057209, 2023). "ZNF460 is a member of the ZNFs family, and overexpression of ZNF460 can predict worse survival in colon cancer." (PMID 35860577, 2022). "Mechanistically, we revealed that ZNF460 promotes the activation of the JAK2/STAT3 signaling pathway in colon cancer cells." (PMID 33976729, 2021). "Mechanistically, we revealed that ZNF460 promotes metastasis through JAK2/STAT3 signaling pathway in colon cancer cells." (PMID 33976729, 2021). "In summary, we found that ZNF460 was overexpressed in colon cancer, and its expression was correlated with clinical outcome." (PMID 33976729, 2021). "To further examine the ZNF460 expression and its clinicopathological characteristics in colon cancer, we performed IHC staining in 214 paraffin-embedded colon cancer specimens." (PMID 33976729, 2021). "Consistent with previous studies, our study also indicated ZNF460 promoted colon cancer invasion and migration, especially lymph node metastasis." (PMID 33976729, 2021). "In this study, we first showed that ZNF460 was overexpressed in colon cancer specimens, was significantly correlated with poor survival, and promoted the invasion and metastasis of colon cancer." (PMID 33976729, 2021). "Further to verify the expression of ZNF460 in colon cancer tissues, we examined ZNF460 expression in 48 paired colon cancer tissue samples and the corresponding adjacent tissues by IHC and WB (1:500; Proteintech, Wuhan, China)." (PMID 33976729, 2021). "To further investigate the functions of ZNF460 in colon cancer cell invasion and migration, we first use WB analyses of ZNF460 expression in the indicated colon cancer cell lines." (PMID 33976729, 2021). "Taken together, the data indicated that ZNF460 high expression predicted a worse survival and was an independent prognostic factor for the patients with colon cancer." (PMID 33976729, 2021). "Consistent with the mRNA expression, data from CPTAC showed that ZNF460 protein expression were also significantly upregulated in colon cancer compared to normal samples (P<0.01)." (PMID 33976729, 2021). "Multivariate analyses revealed that ZNF460 was an independent prognostic factor in patients with colon cancer." (PMID 33976729, 2021). "To further explore the mechanism of ZNF460 in promoting the invasion and metastasis of colon cancer, we found that ZNF460 activated JAK2/STAT3 signaling pathway." (PMID 33976729, 2021). "The IHC results showed that ZNF460 protein of 79.2% (38/48) patients was highly expressed in the colon cancer tissue samples." (PMID 33976729, 2021). "Unpaired colon cancer and normal tissues from TCGA indicated ZNF460 mRNA in colon cancer markedly upregulated expression (P<0.001)." (PMID 33976729, 2021). "However, the expression of ZNF460 in colon cancer and its function in the process of colon cancer invasion and metastasis remained unclear." (PMID 33976729, 2021). "The knockdown of ZNF460 suppressed the invasion and metastasis of colon cancer cells in vitro." (PMID 33976729, 2021). "According to the results of bioinformatics analysis, ZNF460 may promote the metastasis of colon cancer by activating the JAK/STAT signaling pathway." (PMID 33976729, 2021).
colon cancer (continued). "Therefore, we speculated that ZNF121 and HMBOX1 played a collaborative role with ZNF460 in carcinogenesis of colon cancer." (PMID 33976729, 2021). "High expression of ZNF460 predicted poor overall survival (OS) and recurrence free survival (RFS) in patients with colon cancer." (PMID 33976729, 2021). "The results showed that downregulation of ZNF460 expression significantly decreased the p-JAK2 and p-STAT3 expression levels in colon cancer cells." (PMID 33976729, 2021). "Multivariate Cox regression analysis demonstrated ZNF460 expression to be an independent prognostic factor for OS and RFS in colon cancer patients." (PMID 33976729, 2021). "The results outlined that high expression of ZNF460 predicted worse OS (log rank P=0.002) and RFS (log rank P=0.003) in colon cancer patient." (PMID 33976729, 2021). "However, as a member of the ZNFs family, the effect of ZNF460 in colon cancer remains unclear." (PMID 33976729, 2021). "In this study, we found that the expression of ZNF460 protein were markedly increased in clinical colon cancer tissues compared with para-cancer non-cancerous tissues by tissue immunohistochemistry (IHC) and western blot (WB)." (PMID 33976729, 2021). "ZNF460 overexpression was significantly associated with poor prognosis and increased metastatic capabilities of human colon cancer by activating JAK2/STAT3 signaling pathway, and ZNF460 might act as a potential prognostic biomarker and therapeutic target." (PMID 33976729, 2021). "Similarly, overexpression of ZNF460 predicts worse survival and promotes metastasis through JAK2/STAT3 signaling pathway in patients with colon cancer." (PMID 34638319, 2021). "In this study, we first demonstrated that ZNF460 is upregulated in colon cancer tissues compared with para-cancer non-cancerous tissues." (PMID 33976729, 2021). "Taken together, overexpression of ZNF460 predicted worse survival and promoted metastasis through JAK2/STAT3 signaling pathway in patient with colon cancer, and could be a novel therapeutic target in colon cancer." (PMID 33976729, 2021). "In addition, we also provided the first evidence that ZNF460 promoted the invasion and metastasis of colon cancer cells through activating the JAK2/STAT3 signaling pathway and might be a novel therapeutic target in colon cancer." (PMID 33976729, 2021).
colorectal cancer (4 papers, 2023 to 2025). A primary or metastatic malignant neoplasm that affects the colon or rectum. "The Rn7sk, Rpph1, Rn7sl1, Rn7sl2, Znf460, Snord17, Snora73b, H1-4, H4c12, and H3c7 genes were discovered to be highly upregulated in the tumor tissue collected from colorectal cancer patients." (PMID 40427657, 2025). "ZNF460 (zinc finger protein 460) is involved in the regulation of multiple cancer processes by JAK2/STAT3 pathway, and its high expression is associated with the proliferation, invasion, and metastasis of colorectal cancer and oral cancer." (PMID 36639776, 2023).
gastric cancer (3 papers, 2024 to 2025). A primary or metastatic malignant neoplasm involving the stomach. "For example, ZNF460 up-regulates COMMD7 to promote the proliferation of acute myeloid leukemia, and ZNF460 mediates epithelial-mesenchymal transformation through trans-activation of APOC1 expression to promote the progression of gastric cancer." (PMID 38914670, 2024).
acute myeloid leukaemia (2 papers, 2024 to 2025). "Shao's research depicts that the transcription factor ZNF460 regulates COMMD7 and impacts acute myeloid leukaemia (AML) progression via the NF‐κB signalling pathway." (PMID 40521987, 2025).
glioblastoma (1 paper, 2022). The most malignant astrocytic tumor (WHO grade IV). "For the remaining seven DEPCGs (ZWILCH, RPGR, ZNF460, ZNF528, QTRT2, C5orf15 and CNTRL), no previous functional associations were found with glioblastoma progression, despite a number of them being associated with other cancer types." (PMID 36497269, 2022).
hepatocellular carcinoma (1 paper, 2025). A malignant tumor that arises from hepatocytes. "Our identification of ZNF460 and SP5 as significantly enriched TF motifs, with their roles in gastric, colorectal, and hepatocellular cancers, suggests that TSp regulatory networks may be broadly dysregulated in multiple cancer types." (PMID 41279024, 2025).
Immunodeficiency (1 paper, 2022). Failure of the immune system to protect the body adequately from infection, due to the absence or insufficiency of some component process or substance. "The best-matched TFs included ZNF460 and ZNF189, which are associated with lymphoma and immunodeficiency, respectively." (PMID 35752626, 2022).
lymph node metastasis (1 paper, 2021). "ZNF460 expression level was significantly associated with the increased depth of invasion (P<0.05), increased lymph node metastasis (P<0.05), distant metastasis (P<0.05), high CA19-9 level (U/ml) (P<0.05) and TNM stage (P<0.05)." (PMID 33976729, 2021).
cancer (7 papers, 2021 to 2025). A tumor composed of atypical neoplastic, often pleomorphic cells that invade other tissues. "In line with this, TF motif enrichment showed differences between the cancer types: KRAB-ZFPs such as ZNF460 were enriched in GP5d and A375 cells, whereas ZNF135 motif was exclusively enriched in GP5d cells." (PMID 40610675, 2025). "Under normal physiological conditions, ZNF460 is both a transcriptional activator and an oncogene, which is constitutionally activated in cancer and plays a crucial role in tumor progression." (PMID 38914670, 2024). "In addition to its traditional role in cancer cell proliferation, invasion, and migration, ZNF460 also promotes cancer development as a transcription factor by altering the expression of other genes in cancer cells." (PMID 38914670, 2024).
tumor (7 papers, 2016 to 2025). "These approaches are expected to further contextualize the molecular insights regarding the HMGB1/ZNF460/BECN1 axis within the broader “tumor ecosystem” framework, thereby offering a more comprehensive strategy to address radiotherapy resistance in CRC." (PMID 41164196, 2025). "The results of this study showed that miR-125a-5p was underexpressed in BC cells and targeted ZNF460 to regulate the proliferation, migration and invasion of BC cells, indicating that miR-125a-5p had significant anti-tumor effects in BC." (PMID 38914670, 2024). "Further analysis of the expression according to tumor stage showed that ZNF460 mRNA were significantly overexpressed in all the stages (P<0.05)." (PMID 33976729, 2021). "Importantly, both ZNF384 and ZNF460 protein expression exhibited an increase in NPC tumor tissues (“T”), while their expression remained relatively low in adjacent normal nasopharynx epithelial tissues (“N”)." (PMID 38049415, 2023). "However, researches on ZNF460 are deficient and this study took the lead in proclaiming the correlation between ZNF460 and tumor biology." (PMID 34925510, 2021). "ZNF460 binds to prediction sites in the CD24 promoter region, and ZNF460 leads to significant induction of CD24 promoter activity, so the up-regulation of CD24 in BC is due in part to CD24 activation during tumor progression." (PMID 38914670, 2024). "For instance, it has been shown that the expression of the tumor-suppressor gene PTEN can be regulated by its miRNA-mediated competitors VAPA, CNOT6L, SERINC1 or ZNF460." (PMID 26812364, 2016).
ZNF460 also shares sentences with these, for which no sentence is quoted: Alpha-thalassemia (1 paper); breast carcinoma (1); leukemia (1); lymphoma (1); mental retardation (1); oral cancer (1); oral squamous cell carcinoma (1); pancreatic cancer (1).